STAT3 (signal transducer and activator of transcription 3)
Diseases named in the same sentence as STAT3 in open-access papers (continued):
Sharing a sentence is not in itself a finding about the gene and the disease.
cancer (continued). "Suppression of STAT3 by siRNA attenuated 4E‐BP1 phosphorylation, cap‐dependent translation, and cell proliferation in a variety of cancer cells." (PMID 32495998, 2020). "Downregulation of JAK2/STAT3/CCND2 signaling to sensitize cells to radiotherapy and impair cancer stemness." (PMID 32872659, 2020). "Therefore, inhibition of STAT3 could induce cancer cell apoptosis." (PMID 32489321, 2020). "IL-22 activates the STAT3 phosphorylation cascade in cancer cells and induces the expression of stem cell markers (SOX2, NANOG, and POU5F1), resulting in increased cancer stemness and tumorigenic potential." (PMID 32670290, 2020). "FGFR can activate multiple downstream pathways, among which the STAT3 pathway and AKT pathway have been reported to be closely related to cancer stemness." (PMID 32457900, 2020). "We also observed the colocalization of p-STAT3 and p-NF-κB/p65 in PAO1-infected lungs, usually occurring in the cancer cells, which reflects potential interaction between STAT3 and NF-κB." (PMID 32849593, 2020). "In addition, our results also revealed that some natural compounds might mediate STAT3 in cancer." (PMID 32486001, 2020). "NFs have a profound impact on ccRCC migration and accelerate the cancer invasion and metastasis, which was mainly through a IL6-induced STAT3 activation." (PMID 31636361, 2020). "An example of gene-specific methylation change includes the cancer cell-induced methylation and concomitant downregulation of the SOCS1 gene in PDAC CAFs, which enhanced cancer cell growth through the STAT3/IGF1 axis." (PMID 32760726, 2020). "The signal transducer and activator of transcription 3 (STAT3) is a key member of the STAT proteins and its oncogene role in cancer has been shown." (PMID 32545648, 2020). "Signal transducer and activator of transcription 3 (STAT3) regulates cell growth, cell survival, angiogenesis, metastasis of cancer cells, and cancer immune evasion by regulating gene expression as a transcription factor." (PMID 32495998, 2020). "Niclosamide has antitumor activity via inhibition of NF-κB, an increase in ROS and blocking of the Wnt/β-catenin, STAT3 and NOTCH signaling pathways but also targets mitochondria in cancer cells." (PMID 31446534, 2020). "Thus, the MAPK, STAT3, and NF-κB signalling pathways may be key targets for cancer therapy." (PMID 32849902, 2020). "GH signaling plays a key role in cancer development and its activation can lead to STAT1, STAT3 and STAT5 signaling." (PMID 32582547, 2020). "Increased expression of HSP90 activates oncogenic protein kinases JAK2/STAT3, PI3K/AKT and MAPK that facilitates cancer cell progression cancer." (PMID 33096691, 2020). "The JAK/STAT3 signaling pathway activated by the IL6/IL-6R/IL-6Rβ (gp130) complex plays a key role in the growth and development of many human cancers." (PMID 33363013, 2020). "Besides, some reports revealed that betulinic acid could regulate STAT3 in many cancer types." (PMID 32486001, 2020). "STAT3 can directly bind to the promoter region of certain lncRNAs, such as SNHG17, DUXAP8 and HAGLROS, and thus contributes to their overexpression in cancers." (PMID 32972405, 2020). "It was reported that the persistent activation of JAK/STAT3, PI3K/AKT, MEK/ERK, Wnt signaling in most cancer lesions leads to numerous genetic and epigenetic alterations." (PMID 32109290, 2020). "STAT3 is a transcription factor with an essential role in EMT, and it is known that its inhibition leads to the reversal of the EMT process in cancer cells." (PMID 33322336, 2020). "Subsequently, we also observed that CD34-overexpressing PKP+ cancer cells increased p-AKT, p-STAT3, and CD44 cancer stemness protein expression, but reduced p-AMPK protein levels according to Western blot analysis." (PMID 32586050, 2020). "IL-6 activates the STAT3 signaling pathway to promote the expression of CD44+ in hepatocellular carcinoma cells and it increases sphere formation when cancer cells are co-cultured with macrophages." (PMID 32326073, 2020).
cancer (continued). "The molecular mechanisms are mainly through targeting some apoptotic pathways in cancer, for example, Bcl-2/Bax, caspases, PI3K/Akt, JAK2/STAT3, MAPK, and AMPK." (PMID 32774302, 2020). "In summary, our findings indicate that CPAP is an important regulator of STAT3-mediated angiogenesis and cancer metastasis; hence, blockage of the interaction between CPAP and STAT3 is a promising strategy for cancer therapy in CPAP-overexpressing HCC cells." (PMID 31511651, 2020). "The culmination of inflammatory mediators (Stat3, IL-6, TNF-alpha) guides to an immuno-suppression and following progression of cancer." (PMID 32570802, 2020). "We discuss how the transcription factors STAT3 and STAT5 participate in the regulation of energy metabolism and their involvement in the regulation of HIF-1α, an important regulator in the cancer hypoxic microenvironment." (PMID 31947710, 2020). "IL-6 activates signal transducer and activator of transcription 3 (STAT3), which is crucial for proliferation of cancer cells." (PMID 33351844, 2020). "STAT molecules (particularly STAT3 and STAT5) are constitutively activated in a large variety of cancers." (PMID 31947710, 2020). "MET and AXL were shown to regulate cancer cell growth, migration, invasion, and drug resistance via altering MAPK/ERK, PI3K/AKT, and STAT3 signaling." (PMID 34766112, 2020). "A previous study reported that STAT3 interacts with FZD2 and plays a critical role in WNT5a/FZD2-mediated cancer cell metastasis." (PMID 32766155, 2020). "FOXD2-AS1 acted as a scaffold for STAT3 and PRMT5, promoting STAT3 transcriptional activity, which is essential to maintain cancer stemness and promote chemotherapeutic resistance." (PMID 31959918, 2020). "CD44 is also included in many of the pathways found to be significantly altered between the cancer cells and epithelial cells and between the cancer cells and redirected cells including the EMT, TNFα_via_NFkB, apoptosis, IL6_JAK_STAT3 and IL2_STAT5 pathways." (PMID 32774772, 2020). "Most of these targets constitute the key components of the major pathways regulated by GS in cancer cells such as the NF-κB pathway; the intrinsic mitochondrial apoptotic pathway; the JAK/STAT pathway and the STAT3 pathway." (PMID 36046484, 2020). "Signal transducer and activator of transcription 3 (STAT3) plays a key role in the tumorigenesis and cancer stem cells." (PMID 32232002, 2020). "Also, it exhibited chemopreventive properties, such as genoprotective and antiproliferative ones, by inhibiting DNA damage and STAT3 (signal transducer and activator of transcription 3) activation induced by environmental pollutants and through affecting multiple cascades involved in cancer growth." (PMID 32252311, 2020). "miR-1207-5p, 505, and 148a also suppress cancer metastasis by suppressing the expression of corresponding genes via inhibition of AKT and STAT3 activation." (PMID 31952344, 2020). "Based on the results obtained from this study, we concluded that HJC0152 exerts its anti‐cancer effect on human NSCLC at least partially via regulating STAT3 signalling and metabolic processes regulated by STAT3." (PMID 32022328, 2020). "HNRNPs participated in cancer‐related pathways including protein secretion, mitotic spindle, G2/M checkpoint, DNA repair, IL6/JAK/STAT3 signal and coagulation, of which hnRNP genes of HNRNPF, HNRNPH2, HNRNPU and HNRNPUL1 are more likely to be implicated." (PMID 32915499, 2020). "In contrast, aberrant expression of STAT3, HIF1 α, NF-κB, AP-1 and FoxM1 are often observed in different types of cancers." (PMID 33053689, 2020). "In line with this, another study reported an upregulation of STAT3 and mitogen-activated protein kinase (MAPK) signaling in a subpopulation of highly proliferative and invasive PDAC cancer cells upon co-culture of patient-derived PDAC cells with CAFs." (PMID 32752017, 2020).
cancer (continued). "JAK2 is a well-known upstream regulator of STAT3 activation in cancer cells, and the JAK2/STAT3 pathway has been shown to alter the expression of key oncogenes and tumor suppressor genes to enhance the growth, survival, and metastasis of CRC cells." (PMID 32273843, 2020). "Signal transducer and activator of transcription 3 (STAT3) plays important roles in the genesis and development of many types of cancer." (PMID 32161621, 2020). "Three of these proteins—STAT1, STAT3, and STAT5—have been reported to be involved in cancer development." (PMID 33003453, 2020). "The cytokines IL-6 and TNF-α and transcription factors, STAT3 and NFKB contribute to both inflammation and cancer development." (PMID 32731413, 2020). "Among the signaling pathways, STAT-3 is the main transactivator downstream of IL-6 signaling, and IL-6 is involved in the activation of oncogenic STAT-3 in many kinds of cancer." (PMID 32855767, 2020). "We employed CR1 to block exogenous activation of C3 and detected a weakened expression of p-STAT3 and IL-6 compared with AG490-treated cancer cells." (PMID 31928530, 2020). "STAT1 is known to play a prominent role as an activator of the antitumor immune response, while STAT3 and STAT5 are primarily involved in promoting cancer progression." (PMID 33003453, 2020). "The consequentially increased expression of RIP1 promotes the RIP1–Src/STAT3–EMT pathway, resulting in the promotion of radiation-induced cancer cell invasion." (PMID 32605153, 2020). "In accordance with the previous studies, STAT3 acts as a possible target of PTPN2 by dephosphorylation and the levels of p‐STAT3 are dramatically elevated in various cancer cell lines." (PMID 32285621, 2020). "Constitutive activation of STAT3 and increased expression of STAT3 have been well demonstrated in EBV-related cancers and KSHV tumors." (PMID 32735617, 2020). "In addition, the STAT3 signalling inhibition may promote apoptosis in human cancers." (PMID 31568643, 2020). "STAT molecules play diverse pro- and anti-tumorigenic roles in cancer, however, in CRC high STAT3 expression is positively correlated to a better overall survival." (PMID 33014816, 2020). "Treatment with STAT3 or STAT5 ODNs inhibits cell growth and/or induces apoptosis by preventing nuclear translocation of STAT3/5 in cancer cells." (PMID 31963765, 2020). "IL-6 activates the JAK/STAT3 pathway and promotes angiogenesis, invasion, metastasis, and TNF-α activate EMT and promote cancer progression." (PMID 32796516, 2020). "Mechanistically, activation of STAT3 contributes to the induction of EMT and cancer stemness by IGF-IR." (PMID 32493414, 2020). "By STRING, it was shown that ZEB1 can also directly bind to a variety of proteins (e.g., STAT3 and TWIST) regulating cell adhesion, migration and epithelial cell proliferation, and work together on cancer occurrence and progression." (PMID 33392180, 2020). "PTK6 interacts with the EGFR family—including EGFR, HER2, HER3—and aggravates cancer through activation of RAS/MAPK, PI3K/AKT, and STAT3." (PMID 31952344, 2020). "Consistently, immunofluorescence analysis revealed the relatively weak co-expression as well as co-localization of STAT3 and IKKα in MCF-10A cells, whereas MDA-MB-231 cancer cells exhibited much stronger fluorescence intensity of both proteins." (PMID 33396715, 2020). "Signal transducer and activator of transcription 3 (STAT3) is a validated anticancer target due to the relationship between its constitutive activation and malignant tumors." (PMID 32752073, 2020). "In terms of molecular pathways, oncogenic ones, such as STAT3, NF-κB, and PI3K, that are involved in cancer growth and metastasis, are suppressed upon chrysin administration." (PMID 32992587, 2020). "In the present study, we explored the relationship between VDR expression and STAT3 phosphorylation in PTC patients, as well as investigated the adjuvant anti‐cancer activity of Calcitriol and its potential mechanisms." (PMID 32285621, 2020).
cancer (continued). "Herein, we show that MH-mediated inhibition of p-STAT3 in breast (MDA-MB-231) and lung (A549) cancer cell lines is accompanied by decreased levels of gp130 and p-JAK2, two upstream components of the IL-6 receptor (IL-6R) signaling pathway." (PMID 31491838, 2019). "Dysregulation of signal transducer and activator of transcription 3 (STAT3), a classic oncogenic transcription factor regulating the expression of a wide range of genes, has been reported in 50–90% of all human cancers including GBM." (PMID 31277685, 2019). "Signal transducer and activator of transcription (STAT) 3 enriches cancer stem cell through upregulating ANGPTL4, and STAT3 inhibitor abrogated STAT3 binding to the ANGPTL4 promoter and exhibited anticancer activity." (PMID 31717924, 2019). "For example, STAT3 activated by IL6 directly upregulated the miR-21 and miR-181b-1, which was shown to be necessary for the epigenetic switch linking inflammation to cancer." (PMID 30927925, 2019). "We decided to investigate the level of phosphorylated STAT3 over periods (0.5, 2, 6, 24, and 48 h) in the lung (A549) and breast (MDA-MB-231) cancer cells lines treated with 1 and 2.5 μM of PTC-209." (PMID 31695609, 2019). "In our and others’ previous work, Src activated Stat3 and FAK/cortactin signaling and promoted migration and invasion of cancer cells." (PMID 31731716, 2019). "Upon the formation of IL-11/IL-11R/GP130 hexameric complex, IL-11 mainly mediated cancer development through the induction and activation of the JAK/STAT3 signaling pathway." (PMID 30736824, 2019). "Persistent initiation of STAT3 and STAT5 are described in a few human cancer cell lines, and clinical samples." (PMID 30847297, 2019). "For instance, a small-molecule inhibitor of STAT-3, BBI608, has been reported to significantly inhibit cancer stemness in a variety of cancer types, whereas the results from some of the recent clinical trials were discouraging." (PMID 31417869, 2019). "For instance, piceatannol suppresses the proliferation of cancer cells by mitochondria-mediated intrinsic pathways, including the PI3K/AKT1/mTOR, spleen tyrosine kinase, cyclooxygenase-2, and IL-6/STAT3 pathways." (PMID 31517069, 2019). "This evasion of immunosurveillance is achieved by alterations, including loss or downregulation of human leucocyte antigens (HLAs) expression, impaired recognition of cancer cells by T cells and activation of MAPK, STAT3 and β-catenin/Wnt signalling pathways." (PMID 31308358, 2019). "M2 macrophages harbouring TAM can be activated by STAT3 and STAT6 transcriptional factors which allow the M2 macrophages to promote cancer advancement." (PMID 30931335, 2019). "Thus, targeting STAT3 may be an important strategy in cancer treatment." (PMID 31684051, 2019). "Signal transducer and activator of transcription-3 (STAT3) and STAT5 are aberrantly activated through tyrosine phosphorylation in a wide variety of cancer types, including EOC." (PMID 31861720, 2019). "APN was, in fact, able to inhibit leptin-induced cancer invasion, which requires the inactivation of the JAK/STAT3 pathway and the stimulation of AMPK signaling." (PMID 31212761, 2019). "STAT3 and STAT5 are the key nodes in transcriptional activation downstream of cytokine or kinase action in multiple cancers." (PMID 31817042, 2019). "The immunofluorescence analysis with anti-PAK1 and anti-Stat3 in cancer cells indicated that PAK1 and Stat3 colocalize in the nucleus." (PMID 31658701, 2019). "This review focuses on sesquiterpene lactones able to downmodulate STAT3 signaling leading to an antitumor effect and correlates the anti-STAT3 activity with their ability to decrease GSH levels in cancer cells." (PMID 31781335, 2019). "The treatment of siELK3 LCM suppressed ERK1/2 or STAT3 signaling pathway of MDA-MB-231, which are representative oncogenic signaling pathways of various cancers." (PMID 31182803, 2019).
cancer (continued). "As PTPRD-inactivated cancers are more dependent on ERK and STAT3 signaling, it seems plausible that PTPRD-inactivated cancers are more vulnerable to metformin due to its inhibition of both critical signaling pathways." (PMID 31805999, 2019). "Further JAK2 phosphorylation also correlates with both STAT3 and STAT5 phosphorylation, suggesting that the JAK2/STAT3 and JAK2/STAT5 pathways are functional in these cancer cells." (PMID 31817106, 2019). "Upon iper-modulation of STAT3 in TAM, they can promote stemness, survival and proliferation in cancer cells while the latest cells can induce the immunosuppressive properties of TAM, leading to the impairment of cancer immune-surveillance." (PMID 31758404, 2019). "Moreover, cells with the different status of STAT3 also displayed the expression differences of the ERS- and autophagy-associated proteins upon cisplatin treatment, indicating that cancer cells may control their fate through ERS and autophagy in response to cisplatin treatment." (PMID 31597912, 2019). "It was found that preventing the expression of STAT3, STAT5A and STAT5B is related to the enhanced apoptosis in cancer cells." (PMID 31569687, 2019). "We discuss these roles for STAT3 and STAT5, and weigh the attractiveness of different modes of targeting each cancer therapy." (PMID 31684144, 2019). "A novel STAT3 inhibitor, STX-0119 has been identified and showed anti-cancer effect with low toxicity." (PMID 32257917, 2019). "In cancer cells driven by diverse receptor tyrosine kinases (RTKs) (EGFR, HER2, ALK, and MET), MEK inhibitors drive feedback activation of STAT3 through FGFR and JAKs, resulting in therapy failure." (PMID 31684144, 2019). "Given the constitutive activation and critical oncogenic roles of STAT3 in HCC and other cancer types, the STAT3 signaling pathway has emerged as a promising target for pharmacological intervention in cancer treatment." (PMID 31731457, 2019). "However, these natural-derived STAT3/5 inhibitors have exhibited limited efficacy in clinical trials so far, and additional studies are required to clearly establish their utility as a monotherapy or in combination regimens with existing drugs for cancer patients." (PMID 30847297, 2019). "We found that JAK2 and STAT3 were reduced after LDR treatment in both 850-5C and BCPAP cancer cells." (PMID 30760304, 2019). "Collectively, oncogenic MCT-1 activation stimulates the IL-6/IL-6R/Stat3 axis that enhances EMT progression, cancer stemness and M2 polarization in the TNBC system." (PMID 30885232, 2019). "Existing evidences report that several key transcription factors contribute to the up-regulation of lncRNA in human cancers, such as SP1, ELK1, STAT3 and YY1." (PMID 31713587, 2019). "Because transducer and activator of transcription 3 (STAT3) contributes to cancer stemness and EGFR-TKI survival, we assume that STAT3 plays a major role in the regulation of HER3 expression." (PMID 31619200, 2019). "STAT3 is a latent transcription factor downstream of the Janus Kinase (JAK) molecular pathway and is known to be aberrantly activated in a wide variety of cancers." (PMID 31438567, 2019). "GM-CSF has been reported to facilitate the maturation and activation of immune cells through STAT3 and STAT5, and promote host defense against cancer and infections." (PMID 30781810, 2019).